RNU6-212P (RNA, U6 small nuclear 212, pseudogene)
Gene: Small nuclear RNA gene on chromosome 15 (59,341,314 to 59,341,417, reverse strand). Ensembl gene ENSG00000199512.
Homologues: Orthologues: chimpanzee U6 (89% identical), macaque U6 (89% identical), dog U6 (65% identical). Paralogues in human: RNU6-378P (84% identical), RNU6-1060P (83% identical), RNU6-485P (83% identical), RNU6-641P (83% identical), RNU6-1075P (82% identical), RNU6-1158P (82% identical), RNU6-24P (82% identical), RNU6-26P (82% identical), RNU6-517P (82% identical), RNU6-701P (82% identical), RNU6-727P (82% identical), RNU6-1011P (81% identical), and 1287 more.